MIR329-2 (microRNA 329-2)
Synonyms: hsa-mir-329-2; MIRN329-2; mir-329-2
Gene: MicroRNA gene on chromosome 14 (101,027,100 to 101,027,183, forward strand). Ensembl gene ENSG00000207762.
Gene Ontology:
Biological process: miRNA-mediated post-transcriptional gene silencing
Cellular component: RISC complex